CD5L (CD5 molecule like)
Diseases named in the same sentence as CD5L in open-access papers (continued):
Sharing a sentence is not in itself a finding about the gene and the disease.
peritonitis (2 papers, 2021). Inflammation of the peritoneum (tissue that lines the abdominal wall and covers most of the organs in the abdomen). "Using a mouse model of zymosan-induced peritonitis, developed by the daily intraperitoneal injection with zymosan for 5 days, peritonitis was more severe in CD5L−/− than in WT mice." (PMID 33920819, 2021). "In thioglycolate induced peritonitis, the acute inflammatory response peaks in 1–2 days and begins to subside in 3–4 days, and CD5L did not influence the neutrophil recruitment in our results." (PMID 34750342, 2021).
serous ovarian cancer (2 papers, 2023). "To determine the expression of CD5L in other tumor cell types, we analyzed five high-grade serous ovarian cancer samples by using single-cell RNA sequencing of six populations including T cells, monocytes, epithelial cells, fibroblasts, natural killer cells, and B cells." (PMID 37100807, 2023).
alcohol (1 paper, 2019). "In this study, down-regulation of CD5L in alcohol-related HCC patients was shown, indicating its potential anti-tumor role in alcohol-related HCC development." (PMID 30755830, 2019).
alcoholic cirrhosis (1 paper, 2025). "In contrast to CD5L’s consistency, TGF-β1 exhibits etiology-specific behavior, which reveals its context-dependent biology, such as viral hepatitis or alcoholic cirrhosis." (PMID 40647574, 2025).
alcoholic liver diseases (1 paper, 2023). A disorder caused by damage to the liver parenchyma due to alcohol consumption. "Study showed that CD5L directly regulated the switch of the pathogenic Th17 cells to non- pathogenic Th17 cells, which were reported as the critical disease-causing cells in alcoholic liver disease." (PMID 36817578, 2023).
Allergy (1 paper, 2022). An allergy is an immune response or reaction to substances that are usually not harmful. "In addition, we observed evidence of intercellular communication via genes implicated in type 2 immunity (CCL11, CCL13, CD5L, IL4, IL5, IL13, IL24) and allergy-linked inflammation (CCL19)." (PMID 35483355, 2022).
anemia (1 paper, 2025). A reduction in the number of red blood cells, the amount of hemoglobin, and/or the volume of packed red blood cells. "Anemia often has underlying conditions such as increased inflammation and oxidative stress, which partly may influence the level of CD5L." (PMID 40227412, 2025). "Of further interest, anaemia (Hb < 120 g/L), also significantly influenced the level of CD5L at 48 months as seen from the ANCOVA model." (PMID 40227412, 2025).
Brain atrophy (1 paper, 2022). Partial or complete wasting (loss) of brain tissue that was once present. "In addition to CD14, CD40L, and MPO relate to the executive function neuropsychological testing domain; CD5L and sRAGE relate to global and regional MRI markers of brain atrophy; CD5L shows marginal association with dementia, and AD dementia." (PMID 36083988, 2022).
dementia (1 paper, 2022). Loss of intellectual abilities interfering with an individual's social and occupational functions. "Marginal associations (p ≤ 0.05) were observed for CD5L and CD14 with incident dementia (HR = 1.20 per SD unit increase in CD5L level; 95% CI = (1.03, 1.41), p = 0.02; (HR = 1.20 per SD unit increase in CD14 level; 95% CI = (1.00, 1.44), p = 0.05)." (PMID 36083988, 2022). "If our findings are confirmed in additional studies, measures to reverse increases in CD5L and its impact on related innate and adaptive immune cells may have preventive implications and offer targets for novel treatments for dementia." (PMID 36083988, 2022). "Finally, we observed nominally significant associations between higher CD5L and increased dementia risk, but these did not achieve FDR≤0.1." (PMID 36083988, 2022). "In addition, higher CD5L was associated with all cause dementia and AD dementia although associations did not meet significance after multiple test correction." (PMID 36083988, 2022).
diabetic kidney disease (1 paper, 2020). Progressive kidney disorder caused by vascular damage to the glomerular capillaries, in patients with diabetes mellitus. "PromarkerD is a proteomics derived test for predicting diabetic kidney disease that measures the concentrations of three plasma protein biomarkers, APOA4, CD5L and IBP3." (PMID 33126588, 2020).
endometriosis (1 paper, 2025). The growth of functional endometrial tissue in anatomic sites outside the uterine body. "The model with the lowest AIC and highest AUC was a 4-protein model including TOP1, HIST1H3A, IGFBP1, and CD5L which discriminated endometriosis cases from controls with an AUC = 0.71 (95%CI = 0.66–0.76) from the conditional logistic regression model." (PMID 40215752, 2025).
experimental autoimmune encephalomyelitis (1 paper, 2021). An autoimmune demyelinating disease of the central nervous system that is produced experimentally in animals by the injection of homogenized brain or spinal cord in Freund's adjuvant. "Both CD4+ T cell-specific conditional p19-deficient mice and complete CD5L-deficient mice showed significantly alleviated experimental autoimmune encephalomyelitis (EAE) with reduced frequency of GM-CSF+CD4+ T cells." (PMID 33664371, 2021).
fatty liver disease (1 paper, 2009). A reversible condition wherein large vacuoles of triglyceride fat accumulate in liver cells via the process of steatosis. "Our CD5L mRNA expression data from pre-cirrhotic NAFLD liver biopsies indicate an increase in association with fatty liver disease which, again, is not altered by the grade of either fat or inflammation." (PMID 19656391, 2009).
hepatitis C (1 paper, 2018). "Two proteins that demonstrated significance by LMM(RF) and LMM(RR) were also previously reported: CD5L (CD5 antigen-like), reported as differentially expressed in hepatitis C patients: and APOA4, (apolipoprotein A-IV), reported as misexpressed in liver metabolic disorders." (PMID 30598095, 2018).
Hypercholesterolemia (1 paper, 2015). An increased concentration of cholesterol in the blood. "Six proteins including retinol-binding protein 4 (RBP4), transthyretin (TTR), gelsolin, haptoglobin, complement factor B (CFB) and CD5 antigen-like protein (CD5L) were identified to play imperative roles in lipid metabolism and inflammatory processes as a consequence of hypercholesterolemia." (PMID 27103892, 2015).
hyperthyroidism (1 paper, 2025). Overactivity of the thyroid gland resulting in overproduction of thyroid hormone and increased metabolic rate. "They showed a significant inverse correlation between CD5L and TSH and a positive correlation between CD5L and fT3 in patients with hypo- and hyperthyroidism, respectively." (PMID 40227412, 2025).
injury (1 paper, 2021). Damage inflicted on the body as the direct or indirect result of an external force, with or without disruption of structural continuity. "In this study, results showed that the expression of CD5L was induced in the development of APAP-induced liver injury." (PMID 34750342, 2021). "Therefore, our findings reveal that CD5L may be a potential therapeutic target for prevention and treatment of APAP-induced liver injury." (PMID 34750342, 2021).
macular degeneration (1 paper, 2022). Loss of vision in the central portion of the retina (macula), secondary to retinal degeneration. "Interestingly, CD5L is expressed in retinal microglial cells and may play a role in macular degeneration." (PMID 36083988, 2022).
Multiple Myeloma (1 paper, 2023). "The combination of markers, including the complement C1 complex, JCHAIN, and CD5L, resulted in a prediction model with an AUC of 0.96 for the identification of multiple myeloma patients across various cancer patients." (PMID 37835457, 2023). "Using differential expression analysis and machine learning, the complement C1 complex, JCHAIN, and CD5L were identified as potential biomarkers for diagnosing multiple myeloma (MM)." (PMID 37835457, 2023). "These markers, including the complement C1 complex, JCHAIN, and CD5L, were combined in a prediction model with high accuracy for identifying multiple myeloma patients." (PMID 37835457, 2023). "As CD5L is a major switch of Th17 cell functional states in vivo, this may indicate that Th17 cell functions are dysregulated in Myeloma Patients." (PMID 37835457, 2023).
myeloid leukemia (1 paper, 2017). A clonal proliferation of myeloid cells and their precursors in the bone marrow, peripheral blood, and spleen. "There is, however, no direct evidence in the literature showing the association of myeloid leukemia (either CML or AML) with differential abundance of TTR and/or CD5L." (PMID 28117336, 2017).
myocardial infarction (1 paper, 2021). Gross necrosis of the myocardium, as a result of interruption of the blood supply to the area, as in coronary thrombosis. "Moreover, the depletion of CD5L shows cardiac effects, such as decreased systolic dysfunction, a decreased incidence of cardiac rupture, and reduction of the infarct size during the acute phase after myocardial infarction, in turn resulting in improved survival rates." (PMID 34629330, 2021).
psoriatic arthritis (1 paper, 2022). Joint inflammation associated with psoriasis. "Psoriatic arthritis was characterized by significantly enhanced production of CD5L." (PMID 36556186, 2022).
respiratory failure (1 paper, 2022). The significant impairment of gas exchange within the lungs resulting in hypoxia, hypercarbia, or both, to the extent that organ tissue perfusion is severely compromised. "Regarding ACLF, we report for the first time a loss of circulating CD5L in this condition and a significant association with circulatory, brain and respiratory failure." (PMID 35330909, 2022).
schizophrenia (1 paper, 2017). A major psychotic disorder characterized by abnormalities in the perception or expression of reality. "Besides, tumor growth factor (TGF)-α, CD5L, cluster of differentiation 40 (CD40), macrophage-derived chemokine and TNF receptor like 2 protein showed potential as predicting markers of schizophrenia relapse." (PMID 28358316, 2017).
selenium deficiency (1 paper, 2025). A nutritional deficiency disease resulting from inadequate selenium levels in the body, which can lead to impaired function of selenoproteins essential for antioxidant defense and thyroid hormone metabolism. "In this study, we tested the hypothesis that CD5L may serve as a biomarker reflecting selenium status and thyroid hormone activity by analysing serum samples from an intervention trial with selenium and CoQ10 in an elderly community-living population with baseline selenium deficiency." (PMID 40227412, 2025).
steatosis (1 paper, 2009). Increased lipid within the cytoplasm of cells. "The level of CD5L was significantly associated with fibrosis independently of age, sex, steatosis or necroinflammation, as assessed by General Linear Model analysis (GLM, SPSS)." (PMID 19656391, 2009). "Mean levels of CD5L were not significantly different between any other histologically defined group (steatosis or the presence or absence of necroinflammation)." (PMID 19656391, 2009).
thyroid disease (1 paper, 2025). "The data support the potential suitability of serum CD5L as an additional marker of TH status, with potential value for pregnancy and thyroid disease." (PMID 39345206, 2025).
cancer (23 papers, 2009 to 2025). A tumor composed of atypical neoplastic, often pleomorphic cells that invade other tissues. "In addition, we find that increased expression of vascular CD5L in cancer patients is associated with bevacizumab resistance and worse overall survival." (PMID 37100807, 2023). "Here, the model identified the downregulation of JCHAIN and CD5L plasma as the most powerful proteins to separate MM from 14 other cancer types." (PMID 37835457, 2023). "In this study, we also explored the potential roles of CD5L, LCAT, and CDC20 in HCC therapy and found their associations with anti-cancer drug sensitivities in HCC cell lines." (PMID 36494696, 2022). "Only one study supports the use of CD5L as a therapy to specifically target and destroy cancer cells via complement activation." (PMID 35205837, 2022). "In Lu and co-workers’ scRNA-Seq dataset (GSE149614), > 66% of macrophages in para-carcinoma tissue expressed CD5L, CETP, MARCO, and CFP, in contrast to < 22% of macrophages in HCC tissue." (PMID 34001107, 2021). "Various mouse models of disease support the notion that CD5L participates in the pathogenesis of inflammatory processes, including cancer, by preventing the apoptosis of macrophages and other cell types." (PMID 29593730, 2018). "Apoptosis inhibitor of macrophage (AIM/CD5L) is a soluble protein belonging to the scavenger receptor cysteine-rich (SRCR) superfamily that contributes to prevention of a wide range of diseases associated with infection, inflammation, and cancer." (PMID 39477921, 2024). "Our data provide a resource for predicting response of the combination therapy and highlight the importance of CD8+T-cell status conversion and exhaustion induced by Macro CD5L+ in influencing the response, suggesting future avenues for cancer treatment optimization." (PMID 38245530, 2024). "Meanwhile, only the expression of EV CD5L correlated with that in cancer tissues." (PMID 33808296, 2021). "However, in cancer tissues, the expression of only CD5L was found to be increased; hence, the EV level of other candidates was not related to the expression in cancer tissues." (PMID 33808296, 2021). "In addition, proteomic analysis of serum-derived EVs of cancer patients and healthy individuals identified seven upregulated proteins in EVs of cancer patients, one of which was protein CD5L, which might act as a potential biomarker for the early detection of this disease from serum samples." (PMID 36826000, 2023). "CD5L, LCAT and CDC20 were shown to be significantly correlated with immune/stroma cell infiltrations, immunoregulators and 31 anti-cancer drug sensitivities in HCC." (PMID 36494696, 2022). "We employed two large-scale bulk HCC RNA-Seq/microarray datasets to compare the expression of HAMP, CD5L, CETP, MARCO, and CFP between HCC and para-carcinoma tissue samples." (PMID 34001107, 2021). "By ELISA assay, although CD5L was markedly elevated in a number of cirrhotic individuals with HCC, its overall ability to distinguish non-cancer from cancer individuals as determined by AUC ROC analysis was poor." (PMID 19656391, 2009). "CD5L mRNA expression was quantified in one set of liver biopsy tissues from patients with histologically staged NAFLD, and a set of normal liver tissues collected at the time of resection for benign or secondary cancers." (PMID 19656391, 2009). "The AUC determined by ROC analysis was 0.495 and indicated a poor serum CD5L discriminatory capacity between cirrhotic individuals with and without cancer." (PMID 19656391, 2009).
tumor (18 papers, 2013 to 2025). "Some of the identified proteins have been shown to inhibit apoptosis or cause tumor cells to adapt to hypoxia, thereby promoting tumor cell survival, including clusterin, CD5L, HYOU1, prosaposin, and hepatocyte growth factor activator." (PMID 35659255, 2022). "GP23 abundance was associated with levels of immunoglobulin M and CD5L, a protein whose overexpression in tumor-associated macrophages correlated with poorer patient prognosis, and it could be an immune checkpoint in macrophages." (PMID 41106480, 2025). "But it was noticeable that the prognostic role of CD5L disappeared when pathological stage was used as strata variable, it was indicated that the effects of CD5L on overall survival was associated with its correlation with the tumor stage." (PMID 30755830, 2019). "Conversely, CD5L, previously recognized for its anti‐tumor properties and positive correlation with CD8+ T cell infiltration and M1 macrophage activity was predominantly expressed in the mac0 subtype in normal tissues." (PMID 40552574, 2025). "Therapeutic antibodies to CD5L are described as potential tumor drugs displaying promising chemotherapeutic effects." (PMID 39345206, 2025). "This transfer reprogrammed TAMs from anti‐tumor CD5L+ to pro‐tumor TREM2+ phenotypes, increasing CCL18 secretion, reducing phagocytic activity, and impairing CD8+ T cell proliferation." (PMID 40552574, 2025). "Based on these results, we classified mac0 as “tumor‐suppressive CD5L+ macrophages” and mac3 as “tumor‐promoting TREM2+ macrophages”." (PMID 40552574, 2025). "Across all analyzed cell types, TREM2 expression was primarily confined to tumor tissues, whereas CD5L was more prevalent in normal tissues." (PMID 40552574, 2025). "We further confirmed the absence of Macro CD5L+ in the control group in the single-cell transcriptome, while the Macro CD5L+ injection group had colonization of Macro CD5L+ in the tumor environment." (PMID 38245530, 2024). "The results showed that Macro CD5L+ cells were much more abundant in tumor samples of patients with poor response to the GOLP regimen than those of patients with good response to the GOLP regimen." (PMID 38245530, 2024). "We sorted Macro CD5L+ (CD45+ F4/80+ FOLR2+) in the tumor environment of orthotopic injection model and injected the sorted Macro CD5L+ into the subcutaneous iCCA model to directly explore its effect on GOLP therapy." (PMID 38245530, 2024). "We detected the presence of Macro CD5L+ in the tumor environment of liver orthotopic injection model, while hardly detected them in the subcutaneous model, suggesting that Macro CD5L+ specifically existed in the liver environment." (PMID 38245530, 2024). "To determine the function of CD5L in tumor angiogenesis, we generated CD5L-overexpressing RF24 endothelial cells." (PMID 37100807, 2023). "To determine possible mechanisms of CD5L elevation in tumor endothelial cells, we next examined the regulation of CD5L gene transcription." (PMID 37100807, 2023). "Mice treated with the isotype control antibody had a larger tumor burden than did mice treated with an effective anti-CD5L antibody." (PMID 37100807, 2023). "Treatment with the two effective anti-CD5L antibodies resulted in significantly lower tumor weights and fewer tumor nodules compared with the control antibody." (PMID 37100807, 2023). "We found that patients with disease resistant to bevacizumab had significantly higher CD5L expression in their tumor endothelial cells than did those with bevacizumab-sensitive disease." (PMID 37100807, 2023). "This suggests that the upregulation of CD5L by tumor endothelial cells is an important component of the adaptive resistance mechanism against bevacizumab treatment." (PMID 37100807, 2023). "We examined the genomic profiles of tumor-associated endothelial cells collected at pretreatment, at the maximal response, and at tumor progression and found substantially elevated CD5L levels at the time of progression." (PMID 37100807, 2023).